NME6 (NME/NM23 nucleoside diphosphate kinase 6)
Description:
Catalytic subunit of a complex with RCC1L, which catalyzes the transfer of a gamma-phosphoryl group from a nucleoside triphosphate, mainly ATP, to a nucleoside diphosphate via a ping-pong mechanism involving the formation of a phosphohistidine intermediate. Participates in the regulation of mitochondrial nucleotide levels, mitoribosome biogenesis, and mitochondrial RNA abundances. Supplies pyrimidine ribonucleoside triphosphates (rNTPs) for mitochondrial transcription and is required for the maintenance of mitochondrial DNA (mtDNA) when the import of pyrimidine deoxyribonucleoside triphosphates (dNTPs) is limited from the cytosol is limited. As a monomer, lacks nucleoside diphosphate kinase (NDPK) activity.
Synonyms: NDK6; IPIA-alpha; NM23-H6; NDK 6
Tractability: No criterion of Open Targets' tractability assessment is met for any kind of drug.
Gene: Protein-coding gene on chromosome 3 (48,290,288 to 48,301,685, reverse strand). Ensembl gene ENSG00000172113.
Subcellular location: Mitochondrion matrix; Mitochondrion inner membrane; Mitochondrion
Subcellular location (Human Protein Atlas): Vesicles
Pathways (Reactome):
Metabolism: Interconversion of nucleotide di- and triphosphates
Gene Ontology:
Molecular function: nucleoside diphosphate kinase activity; protein binding
Biological process: negative regulation of cell growth; negative regulation of mitotic nuclear division; nucleotide metabolic process; pyrimidine ribonucleotide salvage; nucleobase-containing small molecule interconversion; CTP biosynthetic process; GTP biosynthetic process; nucleobase-containing small molecule metabolic process; UTP biosynthetic process
Cellular component: mitochondrial inner membrane; mitochondrial matrix; mitochondrion
Genetic constraint (gnomAD): Loss-of-function variants: 18 observed, 22.97 expected, observed/expected ratio (o/e) 0.78, 90% interval 0.54 to 1.16. The synonymous counts are far from expectation, so gnomAD's model fits this gene poorly and the ratio says little. Missense variants: 216 observed, 238.11 expected, observed/expected ratio (o/e) 0.91, 90% interval 0.81 to 1.01. Synonymous variants: 58 observed, 88.04 expected, observed/expected ratio (o/e) 0.66, 90% interval 0.53 to 0.82.
Homologues: Orthologues: chimpanzee NME6 (100% identical), macaque NME6 (98% identical), pig NME6 (94% identical), dog NME6 (92% identical), rat Nme6 (91% identical), rabbit NME6 (90% identical), mouse Nme6 (89% identical), guinea pig NME6 (70% identical), tropical clawed frog nme6 (65% identical), zebrafish nme6 (60% identical), Drosophila melanogaster nmdyn-D6 (36% identical). Paralogues in human: NME7 (34% identical), NME5 (32% identical), NME8 (28% identical), NME3 (27% identical), NME2 (24% identical), NME4 (24% identical), NME1 (23% identical), NME9 (15% identical).
Diseases named in the same sentence as NME6 in open-access papers:
NME6 is named in the same sentence as 13 diseases in open-access papers, as found by Europe PMC text mining. Sharing a sentence is not in itself a finding about the gene and the disease. The quoted sentences say what the papers report.
breast carcinoma (1 paper, 2024). "Considering the multifunctional role of NME family members, the goal of the present study was to assess the influence of the overexpression or silencing of NME6 on fundamental cellular events of MDA-MB-231T metastatic breast cancer cells." (PMID 39273527, 2024). "Therefore, proliferation, cell cycle progression, apoptosis, and metastatic potential were investigated after NME6 overexpression or silencing in breast cancer cells." (PMID 39273527, 2024).
colorectal cancer (1 paper, 2024). A primary or metastatic malignant neoplasm that affects the colon or rectum. "NME6 was found to be overexpressed along with NME4 and NME7 in primary colon and gastric carcinomas, while another study revealed that NME6 expression was higher in colorectal cancer tissues." (PMID 39273527, 2024).
Crohn disease (1 paper, 2013). A gastrointestinal disorder characterized by chronic inflammation involving all layers of the intestinal wall, noncaseating granulomas affecting the intestinal wall and regional lymph nodes, and transmural fibrosis. "The expression levels of four genes identified by microarray screening (PLCB2, HVCN1, CTSS, and DEF8) and one purine/thiopurine related gene (NME6) correlated significantly with the clinical activity of Crohn’s disease." (PMID 23437289, 2013). "Five genes (NME6 from the purine/thiopurine network, PLCB2 of the RAC1 network, and HVCN1, CTSS, and DEF8) correlated with the Harvey-Bradshaw index of Crohn’s disease activity." (PMID 23437289, 2013).
liver cancer (1 paper, 2023). An epithelial or non-epithelial malignant neoplasm that arises from the liver. "We next expanded our analysis to liver cancer cell lines, since the expression of NME6 is increased in these cell lines relative to other cancer types (Fig EV3B)." (PMID 37439264, 2023). "The expression of NME6 correlates with an unfavourable prognosis in liver cancer patients (Fig EV3C)." (PMID 37439264, 2023). "For instance, NME6 is upregulated along with the mitochondrial transcription machinery in certain cases of liver cancer and has been linked to negative prognosis." (PMID 37439264, 2023). "It remains to be seen whether the contribution of NME6 to the steady‐state levels of mitochondrial ribonucleotides differs between cell and tissue types, as indicated by the different effects of NME6 in various liver cancer cell lines." (PMID 37439264, 2023). "OXPHOS subunits were diminished in two out of three NME6 knockout human liver cancer cell lines, while the abundance of mtDNA was not affected." (PMID 37439264, 2023).
lymph node metastasis (1 paper, 2025). "ADSL, ADCY3, and NME6 were associated with lymph node metastasis, distant metastasis, and differentiation, whereas APRT and NME3 were independent of these clinical variables." (PMID 40017120, 2025).
melanoma (1 paper, 2025). A malignant, usually aggressive tumor composed of atypical, neoplastic melanocytes. "Although we believe that NME6 is a protective factor for OC, NME6 has been shown to be a melanoma promoter." (PMID 40386292, 2025).
osteosarcoma (1 paper, 2024). A usually aggressive malignant bone-forming mesenchymal neoplasm, predominantly affecting adolescents and young adults. "The overexpression of NME6 in SAOS2 (human osteosarcoma) cells resulted in growth suppression and the formation of multinucleated cells after 72 h; therefore, they concluded that NME6 probably affects cytokinesis." (PMID 39273527, 2024).
Sepsis (1 paper, 2022). Sepsis is defined as life-threatening organ dysfunction caused by a dysregulated host response to infection. "Therefore, NME6 may influence the outcome of sepsis by involving ATP metabolism." (PMID 35265105, 2022). "Meanwhile, the present study identified eight metabolism-related genes (NME1, NME6, POLD4, POLE4, POLR2J, POLR2L, ADCY3, and ENTPD1) in patients with sepsis and the identified metabolism-related genes may represent diagnostic and therapeutic biomarkers of sepsis." (PMID 35265105, 2022).
cancer (6 papers, 2016 to 2025). A tumor composed of atypical neoplastic, often pleomorphic cells that invade other tissues. "Upregulated NME6 has been associated with progression and unfavorable outcomes in some cancers, potentially positioning NME6 as a promising diagnostic or prognostic marker or even as a target for anticancer therapies." (PMID 39120309, 2024). "The NME6+ epithelial cell high-expression group had a greater prognosis and showed a negative connection with the tumor immune dysfunction and exclusion score and cancer-associated fibroblast cell concentration." (PMID 40386292, 2025). "Moreover, analyses from publicly available databases suggest a potential association between NME6 functions and cancer progression." (PMID 39120309, 2024). "Together, this set of data provides support from cancer cell line and clinical datasets that NME6 function may be linked to liver cancer progression." (PMID 37457379, 2023). "The number of NME6+ epithelial cells showed significant differences in the TIDE scores and the amount of cancer-associated fibroblast content, and they were all significantly negatively correlated." (PMID 40386292, 2025). "For instance, CRISPR KO screens indicate an intrinsic dependency on NME6 expression in many cancer cells." (PMID 39120309, 2024). "This minimal set of data from freely available databases addresses several of the key outputs of a target evaluation study, which mitigates the risk associated with committing resource to further exploration of NME6 as a novel anti-cancer drug target." (PMID 37457379, 2023). "A minimal set of databases can be used to support the unbiased evaluation of NME6 as a novel anti-cancer drug target." (PMID 37457379, 2023). "A recent bioRxiv preprint proposes that NME6 regulates mitochondrial gene expression and should be considered a novel target in diseases in which mitochondrial gene transcription is altered, including cancer." (PMID 37457379, 2023). "There is emerging evidence for a predominant role of NME6 in matrix (d)NTP supply and mitochondrial function in rapidly proliferating cancer cells." (PMID 39120309, 2024). "In our previous studies, we chose sponge and human cancer-related homologs with an already determined localization in human cancer cells, namely NME1) and NME6." (PMID 36827160, 2023). "A PubMed search of ‘NME6 AND Cancer’ gives only three results, none of which provide sufficient data to identify NME6 as a novel anti-cancer drug target." (PMID 37457379, 2023).
tumor (4 papers, 2023 to 2025). "Clinically, elevated NME6 expression significantly correlates with poorer patient outcomes in several tumor types, most notably again in liver hepatocellular carcinoma." (PMID 39120309, 2024). "In these pathways, some genes including an oxidative stress response gene (GSTO1), a metastasis suppressor gene (NME6), and a gene involved in tumor cell survival (UCKL1), were upregulated." (PMID 37744913, 2023). "Several studies have reported upregulated NME6 mRNA in tumor tissue, with some cases linking it to a negative prognosis, including in colorectal and liver cancer." (PMID 39120309, 2024). "However, genes involved in antioxidant defense (GSTO1), apoptosis process (DUSP8), and tumor suppressor (KIAA1324, FBXO47, NME6) were upregulated in mycotoxins-exposed animals, suggesting activation of the antioxidant defense in response to mycotoxicity." (PMID 37744913, 2023).
NME6 also shares sentences with these, for which no sentence is quoted: infection (2 papers); chondropathies (1); gastric carcinoma (1).